ZNF735 (zinc finger protein 735)
Description:
May be involved in transcriptional regulation.
Synonyms: ZNF735P
Tractability: PROTAC: ubiquitination databases record sites on it.
Gene: Protein-coding gene on chromosome 7 (64,207,203 to 64,220,290, forward strand). Ensembl gene ENSG00000223614.
Subcellular location: Nucleus
Pathways (Reactome):
Gene expression (Transcription): Generic Transcription Pathway
Gene Ontology:
Molecular function: DNA-binding transcription factor activity, RNA polymerase II-specific; RNA polymerase II cis-regulatory region sequence-specific DNA binding
Biological process: regulation of DNA-templated transcription; regulation of transcription by RNA polymerase II
Cellular component: nucleus
Genetic constraint (gnomAD): Loss-of-function variants: 10 observed, 10.79 expected, observed/expected ratio (o/e) 0.93, 90% interval 0.57 to 1.56. The upper end of that interval is the gene's LOEUF score, 1.56, which puts it in group 6 of 6, group 1 being the genes least tolerant of losing a copy. Missense variants: 487 observed, 463.56 expected, observed/expected ratio (o/e) 1.05, 90% interval 0.98 to 1.13. Synonymous variants: 168 observed, 156.06 expected, observed/expected ratio (o/e) 1.08, 90% interval 0.95 to 1.22.
Homologues: Orthologues: macaque ZNF735 (89% identical). Paralogues in human: ZNF722 (83% identical), ZNF679 (81% identical), ZNF716 (80% identical), ZNF254 (67% identical), ZNF728 (66% identical), ZNF708 (66% identical), ZNF726 (66% identical), ZNF506 (64% identical), ZNF486 (63% identical), ZNF90 (62% identical), ZNF676 (60% identical), ZNF492 (58% identical), and 164 more.